CHRDL1 (chordin like 1)
Diseases named in the same sentence as CHRDL1 in open-access papers (continued):
Sharing a sentence is not in itself a finding about the gene and the disease.
Obesity (5 papers, 2018 to 2023). Accumulation of substantial excess body fat. "Overall, our findings support the pro-adipogenic role of CHRDL1 as a new adipokine and pave the way toward animal studies and future research on its clinical implications and development of anti-obesity therapy." (PMID 36831292, 2023). "Our findings support a pro-adipogenic role of CHRDL1 as a new adipokine and pave the way toward animal studies and future research on its clinical implications and development of anti-obesity therapy." (PMID 36831292, 2023). "We then utilized the PPI network to predict the mechanism of CHRDL1 in inducing obesity of PCOS patients, and the BMP4 signaling and IGF1 were identified." (PMID 33910166, 2021). "We utilized the protein-protein-interaction (PPI) network by GeneMANIA to analyze the DEGs, and predict the mechanism of CHRDL1 in inducing obesity in PCOS patients." (PMID 33910166, 2021). "Further studies should be conducted to investigate the actual relationship and mechanism between CHRDL1 and the obesity status of PCOS." (PMID 33910166, 2021). "The expression of CHRDL1 was significantly higher in obesity PCOS cases than the BMI matched healthy controls (p = 0.0415)." (PMID 33910166, 2021). "Then, the linear regression analysis was performed between the genes and BMI index, and finally, the gene CHRDL1 was found potentially responsible for the obesity status of PCOS patients." (PMID 33910166, 2021). "We then utilized the PPI network to predict the mechanisms of CHRDL1 in inducing obesity in PCOS patients." (PMID 33910166, 2021). "Further studies should be made to figure out the relationship between CHRDL1 and obesity." (PMID 33910166, 2021). "Considering the close association between CHRDL1 and BMP4, the role of BMP4 in PCOS and obesity may point out the potential role and mechanism of CHRDL1 in PCOS or obesity." (PMID 33910166, 2021). "However, several limitations exist with this study, most importantly, the present study was based on bioinformatic analysis, but not functional; further experimental and functional studies need to be performed for exploring the role of CHRDL1 in obesity of PCOS." (PMID 33910166, 2021). "The role of CHRDL1 in PCOS is rarely researched, but it has been related to obesity in a few researches." (PMID 33910166, 2021). "LBP can suppress the PA-induced osteoblast apoptosis through the miR-200b-3p/Chrdl1/PPARγ axis, which has also verified that LBP shows certain protection on the obesity-induced osteoporosis." (PMID 33447177, 2020). "Then, the linear regression analysis was performed between the genes and BMI index, and finally, the gene CHRDL1 was found potentially responsible for the obesity status of PCOS patients, which was not for non-PCOS cases." (PMID 33910166, 2021). "LBP suppresses the PA-induced osteoblast apoptosis via the miR-200b-3p/Chrdl1/PPARγ axis to play a protective role for obesity-induced osteoporosis, but miR-200b-3p/Chrdl1/PPARγ is not the only mechanism for LBPs protecting osteoblasts from PA." (PMID 33447177, 2020). "However, the relationship between CHRDL1 and PCOS/obesity was rarely researched." (PMID 33910166, 2021). "In summary, the present study identified the gene CHRDL1 that may be responsible for the obesity of PCOS patients, but not for non-PCOS cases." (PMID 33910166, 2021). "However, the relationship between CHRDL1 and PCOS or obesity was rarely researched." (PMID 33910166, 2021). "Moreover, considering the findings of this paper, the BMP4 inhibitor CHRDL1 is highly expressed in obesity but not in lean PCOS cases; the CHRDL1 gene may functions differently in normal or PCOS cases." (PMID 33910166, 2021).
oral squamous cell carcinoma (5 papers, 2022 to 2024). "Nonetheless, the specific biological functions and underlying mechanisms of CHRDL1 in oral squamous cell carcinoma (OSCC) remain largely unexplored." (PMID 39462350, 2024). "According to the literature, CHRDL1 is associated with a worse prognosis in oral squamous cell carcinoma, where it also regulates metastasis and EMT." (PMID 36497175, 2022). "However, the exact function and molecular mechanism of CHRDL1 in oral squamous cell carcinoma (OSCC) remain unclear." (PMID 35494000, 2022).
lung carcinoma (4 papers, 2021 to 2025). "Apparently, CHRDL1 is a tumor suppressor gene that can induce early apoptosis in the lung cancer cell line." (PMID 35205284, 2022). "To ascertain whether CHRDL1 was a tumor suppressor gene in lung cancer, we performed an apoptosis analysis." (PMID 35205284, 2022). "In our study, we performed an apoptosis analysis to investigate the role of CHRDL1 in lung cancer." (PMID 35205284, 2022). "Especially, five lung cancer-related genes including CYP4B1, CHRDL1, SFTPC, SFTPB, and AGER were consistently downregulated in both LUAD and LUSC had a positive correlation with TMPRSS2, exhibited an opposite effect on the prognosis of LUAD and LUSC." (PMID 35082790, 2021).
glaucoma (3 papers, 2014 to 2025). Increased pressure in the eyeball due to obstruction of the outflow of aqueous humor. "Mutations in Chordin-Like 1 (CHRDL1) cause XMC, characterized by anterior segment enlargement, mosaic corneal dystrophy, premature cataracts, and glaucoma." (PMID 41210874, 2025). "A mutation in the X-chromosomal gene CHRDL1 was identified in a patient with primary megalocornea but not glaucoma." (PMID 35011756, 2021). "Since we have shown that CHRDL1 mutations do not lead to increased IOP or glaucoma, the repeated examinations that are required to monitor IOP (under anaesthesia) for PCG patients are not required for MGC1 patients." (PMID 25093588, 2014). "Notably, in the eight reported unrelated MGC1 families with CHRDL1 mutations, none of the affected males (ranging from 8–72 years of age) had raised IOP, glaucoma or significant visual loss." (PMID 25093588, 2014).
glioma (3 papers, 2022 to 2025). A benign or malignant brain and spinal cord tumor that arises from glial cells (astrocytes, oligodendrocytes, ependymal cells). "Clinically it is interesting to note that CHRDL1 is, according to data from the human protein atlas, associated with worse survival in glioma, as well as in urothelial and renal cancer." (PMID 36497175, 2022). "Lastly, we interrogated the human protein atlas in order to unravel the relevance of CHRDL1 for patient outcomes and observed that high CHRDL1 expression was associated with worse clinical outcomes in glioma, while it could also be considered unfavourable in urothelial and renal cancer." (PMID 36497175, 2022). "Chordin-like 1 (CHRDL1) has been identified as an “enforcer of stemness” in glioma stem cells, via antagonism of BMP4-induced glioblastoma differentiation and reduced tumorigenicity." (PMID 40277903, 2025). "In this article, we research Chordin-like 1 (CHRDL1), a secreted protein, as a potential key regulator of the glioma stem-like cell (GSC) phenotype." (PMID 36497175, 2022).
COVID-19 (2 papers, 2020 to 2023). A disease caused by infection with severe acute respiratory syndrome coronavirus 2. "For the first time, we reported elevated plasma NPDC1 and CHRDL1 in patients with COVID-19 with comorbidities." (PMID 37047248, 2023).
lymph node metastasis (2 papers, 2017 to 2021). "However, low CHRDL1 expression was significantly correlated with local invasion, lymph node metastasis and TNM stage (p < 0.05)." (PMID 28423564, 2017). "The transcription levels of CTGF, CYR61, FGF13, CHRDL1, and OGN were significantly higher in health controls than in THCA patients in the subgroup analyses involving disease stage, lymph node metastasis, gender, and age." (PMID 33816258, 2021).
pancreatic adenocarcinoma (2 papers, 2023 to 2025). "In 21 type of cancers, including pancreatic adenocarcinoma (PAAD), COAD, STAD, READ, LUAD, LUSC, CHRDL1 showed strong positive correlations with hematopoietic." (PMID 40230414, 2025).
pancreatic cancer (2 papers, 2021 to 2025). "Currently, the potential role of CHRDL1 in pancreatic cancer remains unreported, and its underlying mechanisms require further investigation." (PMID 40837015, 2025). "Meanwhile, lower CHRDL1 expression was associated with poorer prognosis in pancreatic cancer patients." (PMID 40837015, 2025). "The enhanced dependence on the BMP/SMAD1/5/9 pathway in SMAD4-deficient contexts could potentially explain why CHRDL1 exhibits more pronounced metastasis-suppressing effects in pancreatic cancer." (PMID 40837015, 2025). "Moreover, higher CHRDL1 expression was positively associated with improved overall survival, suggesting a potential protective role in pancreatic cancer." (PMID 40837015, 2025). "Our research aimed to discover the role of CHRDL1 in pancreatic cancer cells and investigate the associated mechanisms, which could lead to the discovery of a new target for clinical treatment." (PMID 40837015, 2025). "As a BMP antagonist, CHRDL1 desensitizes pancreatic cancer cells to BMP-4, thereby inhibiting BMP-mediated SMAD1/5/9 signaling." (PMID 40837015, 2025). "In our study, we found that CHRDL1 expression was lower in pancreatic cancer tissues compared to adjacent tissues using RT-qPCR, Western blotting, and immunohistochemistry." (PMID 40837015, 2025). "To further examine the functional impact of CHRDL1 in pancreatic cancer metastasis, we intravenously injected CHRDL1-transfected tumor cells into nude mice and assessed their metastatic potential." (PMID 40837015, 2025). "CHRDL1 exerts tumor-suppressive effects in pancreatic cancer by inhibiting the BMP4/SMAD pathway, reducing migration, invasion, and metastasis." (PMID 40837015, 2025). "Data from The Cancer Genome Atlas (TCGA) was utilized to explore the correlation between CHRDL1 expression and pancreatic cancer development." (PMID 40837015, 2025). "This suggests that CHRDL1 is lowly expressed in pancreatic cancer and is correlated with poor prognosis in pancreatic cancer patients." (PMID 40837015, 2025). "Overexpression of CHRDL1 inhibited the migration and adhesion of pancreatic cancer cells (PANC-1 and SW1990) and significantly reduced the tumor weight and size in mice." (PMID 40837015, 2025). "This indicates that CHRDL1 exerts its effects on inhibiting the malignant behaviors of pancreatic cancer cells by relying on the inhibition of the BMP/SMAD pathway." (PMID 40837015, 2025). "Ultimately, CHRDL1 suppressed the malignant behaviors of pancreatic cancer cells and the progression of pancreatic cancer in vivo." (PMID 40837015, 2025). "It was found that CHRDL1 was significantly downregulated in pancreatic cancer tumors compared to normal tissues." (PMID 40837015, 2025). "Our study provided evidence that CHRDL1 inhibited the progression of pancreatic cancer in a mouse xenograft model." (PMID 40837015, 2025). "By inhibiting the BMP/SMAD signaling pathway, CHRDL1 might elucidate crucial mechanisms in pancreatic cancer and represented a potential therapeutic target for the treatment of this disease." (PMID 40837015, 2025). "To examine whether CHRDL1 exerts similar phenotypic effects in pancreatic cancer, we conducted functional assays using PANC-1 and SW1990 cell lines." (PMID 40837015, 2025). "This study explores CHRDL1’s function and mechanism in pancreatic cancer." (PMID 40837015, 2025). "Based on these observations, we hypothesized that CHRDL1 may play a regulatory role in pancreatic cancer progression." (PMID 40837015, 2025). "We also aimed to verify whether CHRDL1 regulated the malignant behaviors of pancreatic cancer cells through the BMP/SMAD pathway." (PMID 40837015, 2025). "CHRDL1 was downregulated in pancreatic cancer, correlating with poor prognosis." (PMID 40837015, 2025). "Analysis of the TCGA database indicated that CHRDL1 was downregulated in pancreatic cancer cells." (PMID 40837015, 2025). "To validate this, we examined CHRDL1 expression in pancreatic cancer cell lines (PANC-1, SW1990)." (PMID 40837015, 2025).
pancreatic cancer (continued). "We further investigated whether CHRDL1 plays a role in pancreatic cancer progression." (PMID 40837015, 2025). "Stably transfected pancreatic cancer cell lines (PANC-1, SW1990) with lentivirus-mediated CHRDL1 overexpression were established to assess effects on cell proliferation, migration, and adhesion." (PMID 40837015, 2025).
prostate carcinoma (2 papers, 2021). A carcinoma that arises from epithelial cells of the prostate gland. "Interrogation of the Chandran prostate cancer dataset (60 localized tumors and 63 adjacent, normal prostate) suggests that CHRDL1 is downregulated by prostate tumors in general." (PMID 33585078, 2021). "Our study not only highlights genes modulated by GHSROS, but also genes (such as ZNF467, CHRDL1, and PPP2R2C) that may be generally relevant to prostate cancer progression." (PMID 33585078, 2021). "Upregulation of SPP1 and downregulation of CHRDL1 and CNN1 (genes involved in bone biology) in metastasis from all sites analyzed are found which suggests they are changed early on and could belong to the genes that make prostate cancer metastatic cells bone-gravitating." (PMID 34209195, 2021).
thymoma (2 papers, 2022 to 2023). A neoplasm arising from the epithelial cells of the thymus. "CHRDL1 is downregulated in most malignant tumors (except for thymoma), despite their differing histologic origins." (PMID 35494000, 2022).
triple-negative breast carcinoma (2 papers, 2015 to 2023). An invasive breast carcinoma which is negative for expression of estrogen receptor (ER), progesterone receptor (PR), and human epidermal growth factor receptor 2 (HER2). "For NOG and CHRDL1 we could confirm these findings in parental MDA-MB-231 and HS578T triple negative breast cancer cell lines." (PMID 25973542, 2015).
coloboma (1 paper, 2019). An abnormality in which a part of a structure in one or both eyes is missing. "These included the known human coloboma associated genes (indicated by #): SMOC1, PAX2, VAX1 and ALDH6, in addition to the coloboma candidates from other animal studies CHRDL1 and CYP1B1 (indicated by •)." (PMID 31162046, 2019). "In addition, targeted manipulations of orthologues of both CHRDL1 and CYP1B1 have recently been shown to cause coloboma phenotypes in Xenopus and zebrafish, respectively." (PMID 31162046, 2019).
congenital glaucoma (1 paper, 2021). "One patient with suspected congenital glaucoma revealed CHRDL1 associated X-linked megalocornea." (PMID 35011756, 2021).
esophageal carcinoma (1 paper, 2022). A primary or metastatic malignant neoplasm involving the esophagus. "Furthermore, CHRDL1 was also downregulated in esophageal carcinoma (ESCA)." (PMID 35494000, 2022).
fibrosis (1 paper, 2025). the formation of excess fibrous connective tissue in an organ or tissue in a reparative or reactive process. "We also demonstrated, for the first time, that Chrdl1 exerts strong anti-fibrotic effects when administered systemically days after MI and can effectively reduce existing or on-going fibrosis cardiac fibrosis." (PMID 40963931, 2025).
head and neck squamous cell carcinoma (1 paper, 2022). A squamous cell carcinoma that arises from any of the following anatomic sites: lip and oral cavity, nasal cavity, paranasal sinuses, pharynx, larynx, and salivary glands. "CHRDL1 was downregulated in head and neck squamous cell carcinoma (HNSC), which was consistent with our results." (PMID 35494000, 2022).
Intellectual disability (1 paper, 2014). "Next, we considered the possibility that the extraocular phenotypes may be due to a mutation in an X-linked intellectual disability (XLID) gene in linkage disequilibrium (LD) with the CHRDL1 mutation, or an autosomal ID gene." (PMID 25093588, 2014).
ischemia (1 paper, 2022). A hypoperfusion of the BLOOD through an organ or tissue caused by a PATHOLOGIC CONSTRICTION or obstruction of its BLOOD VESSELS, or an absence of BLOOD CIRCULATION. "We find that absence of Chrdl1 prevents ischemia-induced spine loss in the peri-infarct area and reduces cell death in the core, without impacting gliosis." (PMID 35264691, 2022). "Since we found an increased expression of Chrdl1 in response to ischemia that may hinder synaptic remodeling, we hypothesized that eliminating Chrdl1 could protect spine loss or promote faster spine turnover to compensate for the ischemic damage." (PMID 35264691, 2022). "Blockade of Chrdl1 after ischemia may therefore represent a new approach to promote the neurorestorative roles of BMPs." (PMID 35264691, 2022). "Due to its role in synaptic plasticity, and previous microarray data showing that the expression of different astrocytic genes is altered following MCAO26, we hypothesized that Chrdl1 expression could be regulated in response to ischemia in confined areas of the injured brain." (PMID 35264691, 2022).
ischemic stroke (1 paper, 2022). A stroke disorder caused by obstruction of blood flow to the brain, due to thrombotic (local blood clot formation) or embolic (due to a blood clot or other material traveling from another site) event. "In future it will be important to assess Chrdl1 expression in human tissue after acute injury such as ischemic stroke." (PMID 35264691, 2022).
lentivirus infection (1 paper, 2022). Virus diseases caused by the Lentivirus genus. "CHRDL1 was overexpressed in the CAL27 cell line by lentivirus infection." (PMID 35494000, 2022).
megalocornea (1 paper, 2023). "Mutations in the CHRDL1 gene cause an X-linked genetic disorder called Megalocornea (MGC1, MIM # 309300), which is an ocular anterior segment disorder caused by failure of normal development of the anterior segment of the eye." (PMID 37761873, 2023). "Defects in the CHRDL1 gene give rise to Megalocornea disease, which is characterized by enlarged anterior eye segments." (PMID 37761873, 2023).
metastatic tumors (1 paper, 2021). "CHRDL1 expression stratified the Taylor (N = 150; 27 metastatic tumors) dataset into two groups with a significant, 438-day difference in overall disease-free survival (relapse; Cox P = 0.0062, absolute hazard ratio (HR) = 2.5)." (PMID 33585078, 2021). "DIRAS1, FBXL16, TP53I11, TFF2, and ZNF467 were upregulated in both metastatic tumors and GHSROS-overexpressing PC3 and LNCaP cells, while AASS, CHRDL1, CNTN1, IFI16, and MUM1L1 were downregulated." (PMID 33585078, 2021).
MMR syndrome (1 paper, 2014). "Intriguingly, we identified another novel missense mutation in CHRDL1, c.464G>A; p.(Cys155Tyr) in a male patient with a diagnosis consistent with MMR syndrome." (PMID 25093588, 2014). "Our findings demonstrate that CHRDL1 should be considered and screened in males diagnosed with MMR syndrome." (PMID 25093588, 2014).
neonatal jaundice (1 paper, 2024). A pigmentation disease characterized by a high level of bilirubin in the blood, causing a yellowing of the skin and other tissues of a newborn infant. "The second locus associated with neonatal jaundice is located on the X chromosome, near CHRDL1 gene (rs12400785, OR = 0.80; 95% CI = 0.77, 0.87; p value = 3.4 × 10−11, MAF = 36.6%)." (PMID 39214992, 2024).